INS (insulin)
Diseases named in the same sentence as INS in open-access papers (continued):
Sharing a sentence is not in itself a finding about the gene and the disease.
type 2 diabetes (continued). "Resveratrol consumption (1000 mg/d for 45 days) significantly lowered fasting glucose, insulin concentrations, hemoglobin A-1c levels, and insulin sensitivity (HOMA-IR) in subjects with type 2 diabetes." (PMID 26703752, 2015). "Type 2 diabetes is a metabolic disorder characterized by hyperglycemia resulting from progressive deterioration in pancreatic insulin secretion, insulin resistance in tissues, and inadequate suppression of glucagon production." (PMID 25874236, 2015). "We amalgamated two similar recommendations (concerning initiation of insulin in type 2 diabetes) and replaced one recommendation concerning prescribing non-steroid anti-inflammatory drugs (NSAIDs) with a composite recommendation on risky prescribing." (PMID 26507739, 2015). "It is well know that COPD patients have a higher risk of developing type II diabetes compared to normal subjects, due to the increase in circulating cytokines, in particular TNF-α, that interferes with glucose metabolism and insulin sensitivity." (PMID 25973198, 2015). "In a previous study, ginseng berry extract improved blood glucose levels, ameliorated insulin sensitivity, lowered cholesterol, and decreased body weight in type 2 diabetic mice." (PMID 26161118, 2015). "Glucose-induced insulin secretion is an essential function of pancreatic β-cells that is partially lost in individuals affected by Type 2 diabetes." (PMID 26330140, 2015). "In the context of limited resources, choice of insulin analogue pens/cartridges over human insulin pens/cartridges is questionable given the marginal benefits of insulin analogues for type 2 diabetes and their higher prices (3–13 folds higher)." (PMID 25815201, 2015). "Previous studies demonstrate that a SGLT2i improved insulin sensitivity in patients with type 2 diabetes." (PMID 26606676, 2015). "In Japan, dipeptidyl peptidase 4 (DPP4) inhibitors have become standard therapeutic agents for type 2 diabetes, and numbers of patients receiving insulin therapy combined with DPP4 inhibitors, which is a highly effective regimen, are increasing." (PMID 25780477, 2015). "In a small study of patients with poorly controlled type 2 diabetes, insulin therapy led to an increase in circulating EPCs." (PMID 26089898, 2015). "It is well known that the ability of insulin to stimulate glucose uptake and inhibit hepatic glucose production is impaired at an early stage in type 2 diabetes." (PMID 25615826, 2015). "Among patients with type 2 diabetes, insulin intensification to achieve glycemic targets occurs less often than clinically indicated." (PMID 26353820, 2015). "In hepatocytes isolated from individuals with type 2 diabetes, the basal and insulin-induced activation of PKCι were elevated." (PMID 25822413, 2015). "The OPT2MISE study enrolled 495 adult patients with poorly controlled type 2 diabetes despite an intensified insulin regimen using rapid and slow-acting insulin analogues." (PMID 29632572, 2015). "Exenatide was reported to normalize both first and second phases of glucose-induced insulin secretion in patients with type 2 diabetes during 3-hour intravenous infusion and to provide long-term improvement of beta cell function by chronic treatment." (PMID 25938469, 2015). "Orz is known to increase PPAR-γ protein expression in 3T3-L1 adipocytes, and the activation of PPAR-γ markedly improves insulin sensitivity and glucose tolerance in type 2 diabetes." (PMID 26083118, 2015). "There was little known about her past medical history aside from type 2 diabetes mellitus (T2DM) requiring insulin, hypertension and chronic obstructive pulmonary disease (COPD)." (PMID 25924859, 2015). "A second and more prevalent category, type 2 diabetes, is characterized by a combination of insulin resistance and inadequate compensatory insulin secretory response." (PMID 26088843, 2015).
type 2 diabetes (continued). "There is accumulating evidence from animal studies indicating that high dietary AGE consumption contributes to increased insulin levels, insulin resistance, defects in first phase insulin secretion, and type 2 diabetes." (PMID 26223897, 2015). "As previously reported, 5077 insulin-naïve patients with type 2 diabetes were included in the study." (PMID 28702235, 2015). "The key finding in this study is the significant down-regulation of FA oxidation genes in the skeletal muscle and adipose tissues of MKR mouse model of Type 2 diabetes, and in the pre-diabetic insulin resistant liver of these mice." (PMID 25784953, 2015). "There is overwhelming evidence that early insulin therapy provides neuroprotective effects in patients with Type 2 diabetes who have diminished insulin secretion." (PMID 26430576, 2015). "Insulin/glucose ratio for specific moments of the exercise and control sessions for individuals with type-2 diabetes." (PMID 30873442, 2015). "Type 2 diabetes is a progressive disease, and as such, an increasingly intensive treatment strategy is needed to achieve glycemic control over time, with likely insulin intensification." (PMID 26353820, 2015). "Metformin and glibenclamide are two oral anti-diabetic drugs commonly used for the treatment of type 2 diabetes by improving insulin responsiveness." (PMID 25849717, 2015). "Insulin therapy in elderly people with type 2 diabetes can lead to an improvement of depressive symptoms and does not seem to affect negatively HRQoL of the participants." (PMID 26110026, 2015). "Type 2 diabetes arises from insulin resistance of peripheral tissues followed by dysfunction of β-cells in the pancreas due to metabolic stress." (PMID 25973388, 2015). "The present study was aimed at evaluating the effects of metformin therapy in type 2 diabetes in pregnancy and comparing it with standard treatment insulin." (PMID 25874236, 2015). "Current evidence based on randomized controlled trials and longitudinal studies do not support the notion that vitamin D supplementation can improve hyperglycemia, beta cell secretion or insulin sensitivity in patients with type 2 diabetes." (PMID 25722966, 2015). "The consequence of this reasoning is a decrease in both glucose effectiveness and insulin sensitivity as seen in individuals with type 2 diabetes compared to healthy controls." (PMID 27123439, 2015). "Insulin-stimulated phosphorylation of Akt tended to be lower in myotubes from severely obese donors with type 2 diabetes compared to severely obese donors with normal glucose tolerance (p = 0.11)." (PMID 25790476, 2015). "These diabetic db/db mice exhibited the classical features of type 2 diabetes, such as severe hyperglycemia, high insulin concentrations, and high lipid profiles (total cholesterol, HDL cholesterol, and triglyceride)." (PMID 26606676, 2015). "Second, we only analysed the effects of these uric acid loci on glucose metabolism and insulin secretion in the normal glucose regulation subjects because most of the type 2 diabetes patients were receiving glucose lowering therapy." (PMID 25617895, 2015). "Although impairment in pancreatic insulin secretion is known to precede the clinical diagnosis of type 2 diabetes by up to a decade, fasting blood glucose concentration only rises abnormally once the impairment reaches a critical threshold." (PMID 25950180, 2015). "In patients with type 2 diabetes, 4 weeks of intensive insulin therapy aiming for near-normal glycaemia partially re-established the insulinotropic properties of GIP." (PMID 25613747, 2015). "Lower insulin sensitivity was observed in myotubes from severely obese subjects with type 2 diabetes." (PMID 25790476, 2015). "Plasma insulin declined 15–17 weeks after birth, and the process of type 2 diabetes in this model is similar to that in human beings." (PMID 25849026, 2015).
type 2 diabetes (continued). "Here, we showed that ZG02-ME has stronger anti-diabetic activity than the original compound (ZG01) through decreasing blood glucose, glycated hemoglobin (HbA1c), and insulin levels in a mouse model of type 2 diabetes (db/db mice)." (PMID 26198246, 2015). "Recent data showed that betatrophin was increased in Type 2 Diabetes (T2D), however, its ability to induce insulin production has been questioned." (PMID 26289721, 2015). "Pancreatic β-cells are the sole source of circulating insulin in humans, and impaired secretion of the hormone, which is absolute in type 1 diabetes and relative in type 2 diabetes, is ultimately responsible for the emergence of the frank disease." (PMID 26038943, 2015). "Literature has suggested the utilization of herbal medications for the treatment of insulin dependent and noninsulin dependent diabetes since time immemorial." (PMID 26273667, 2015). "The combination of dipeptidyl peptidase-4 (DPP-4) inhibition with insulin is a glucose lowering strategy for the treatment of type 2 diabetes which has gained considerable interest during recent years." (PMID 26587020, 2015). "Coetzee and Jackson reported that 28.6% patients with type 2 diabetes in pregnancy required supplemental insulin with metformin." (PMID 25874236, 2015). "This delivery route has been used to inject hematopoietic stem cells (CD34+) into patients with type 2 diabetes, improving metabolic control with reduction of insulin requirements." (PMID 25884215, 2015). "These analyses and the role of specific treatment patterns in patients’ adherence to their type 2 diabetes medication regimens will also inform improved educational materials, insulin use training guides, and care and storage of insulin medications." (PMID 26353820, 2015). "The thiazolidinediones or “glitazones” are one class of oral antidiabetic drugs that improve insulin sensitivity in patients with type 2 diabetes." (PMID 26408008, 2015). "Type 2 diabetes (T2D) occurs when there is insufficient insulin release to control blood glucose, due to insulin resistance and impaired β-cell function." (PMID 26720709, 2015). "As progression of type II diabetes, marked elevations of blood insulin and Hb1Ac levels have been observed after long term HFD supply." (PMID 26540072, 2015). "In this regard, GPR40 agonists have been developed as possible agents to stimulate insulin secretion in type 2 diabetes." (PMID 25679385, 2015). "In subjects with type 1 diabetes and in patients with type 2 diabetes who fail to respond adequately to oral therapies, insulin is used to achieve glycaemic control." (PMID 26089898, 2015). "Results from the trials show that Cr supplementation in patients and animals with type 1 and type 2 diabetes can improve both glucose and insulin metabolism; in contrast to some studies rejecting the importance of Cr in treatment of type 2 diabetes." (PMID 25652875, 2015). "Androgen excess in women likely impairs insulin action, e.g. women with polycystic ovarian syndrome (PCOS) are predisposed to type 2 diabetes." (PMID 25903071, 2015). "It has been shown that exogenous administration of IGF1 to type 2 diabetes patients can improve insulin sensitivity; therefore, a direct effect is possible." (PMID 25722973, 2015). "Stxbp5l (also known as tomosyn-2) has been found to play a role in exocytosis regulation of both insulin and acetylcholine, and as such has been nominated as a genetic factor in both type 2 diabetes and neuromuscular disorders." (PMID 26505904, 2015). "Insulin glargine is a basal insulin analog widely used in the management of both type 1 and type 2 diabetes." (PMID 26176017, 2015). "Type 2 Diabetes (T2D) is a chronic disease arising from the development of insulin absence or resistance within the body, and a complex interplay of environmental and genetic factors." (PMID 25852736, 2015).
type 2 diabetes (continued). "The study population (N = 216,816) consisted of all individuals with type 2 diabetes patients with at least one prescription for a non-insulin anti-diabetic drug and were over 18 years of age." (PMID 25894068, 2015). "This analysis utilized data from a double-blind, randomized, placebo-controlled crossover study in 29 patients with type 2 diabetes treated with vildagliptin or placebo on top of stable insulin dose." (PMID 26587020, 2015). "Type 2 diabetes is characterized by a progressive insulin secretory defect within a setting of insulin resistance." (PMID 26078998, 2015). "We demonstrated that glutamine and whole protein low in glutamine ingested prior to intravenous hyperglycemia were similarly effective in restoring first-phase insulin response in a cohort of well-controlled type 2 diabetes patients." (PMID 25811109, 2015). "Thirty-five patients with type 2 diabetes undergoing HD (including 13 insulin-treated patients) were switched from ongoing therapy to linagliptin (5 mg, once daily)." (PMID 25995772, 2015). "Because a variant of ADAMTS9 has been established as a risk factor for type 2 diabetes, we investigated how ADAMTS9/GON-1 is involved in the insulin/IGF-like signaling pathway." (PMID 26218657, 2015). "Most participants with type 2 diabetes were taking insulin (64% [18/28]) or metformin (39% [11/28])." (PMID 25692042, 2015). "However, type 2 diabetes is typified by two key characteristics—hyperglycemia and hyperinsulinemia —and while the disease has historically been defined by blood glucose levels, insulin may be a more sensitive and relevant diagnostic." (PMID 26682540, 2015). "Although the pathogenic mechanisms underlying type 1 and type 2 diabetes are different, both involve a decrease in β-cell mass and, in the case of type 2 diabetes, a lowered capacity to produce and secrete insulin." (PMID 26038943, 2015). "In humans, oral supplementation with probiotics helps to maintain serum insulin concentrations in pregnant women or preserves insulin sensitivity in subjects with impaired glucose tolerance or type 2 diabetes." (PMID 24608927, 2014). "The novel and most remarkable findings of our study were elevation of blood insulin level in type 2 diabetic rats, stimulated insulin release from isolated rat islets, and increased deposition of glycogen in rat liver." (PMID 24860609, 2014). "This randomised crossover 24 week study examined the effect of frequency of meals on body weight, HFC, insulin resistance and beta cell function in type 2 diabetic patients." (PMID 24838678, 2014). "According to the findings relating to health history of the women, most of the women suffered from Type 2 diabetes and used medicines which included oral antidiabetics (60.0%) and insulin (40.0%)." (PMID 24948979, 2014). "Canagliflozin increased UGE and decreased RTG, leading to reductions in PG, insulin, and body weight, and was generally well tolerated in patients with type 2 diabetes." (PMID 25166023, 2014). "A 72-year-old Japanese woman treated with high-dose glucocorticoids for autoimmune hemolytic anemia, as well as intensive insulin therapy for type 2 diabetes, presented with severe hypoglycemia." (PMID 24524438, 2014). "Impairment of insulin-stimulated glucose uptake by skeletal muscle is recognised as an early defect in the pathogenesis of type 2 diabetes, although the ability of alternative stimuli such as exercise/contraction to increase glucose uptake is unaffected." (PMID 24849570, 2014). "In order to evaluate how thyroid disorders interfere with glycemic control, we analysed insulin-treated type 2 diabetes patients with thyroid disease." (PMID 24580798, 2014). "Insulin secretion defect has been recognized as a key determinant for the progression to type 2 diabetes." (PMID 25310839, 2014). "The insulin secretion ability in those seems to drop more rapidly than those having lower sUA as type 2 diabetes duration extends." (PMID 24971368, 2014).
type 2 diabetes (continued). "The main reason that leads to muscle atrophy in type 2 diabetes is the reduction of insulin responsiveness in the muscle." (PMID 24968071, 2014). "In insulin-treated type 2 diabetic patients, addition of metformin improves insulin sensitivity and glycemic control while allowing a reduction in the daily insulin dose." (PMID 25139174, 2014). "It is widely acknowledged that abnormality in insulin secretion and action plays significant role in development of type 2 diabetes." (PMID 24860609, 2014). "In order to assess the different course of disease to insulin treatment of type 2 diabetes we analysed the insulin-free period dependent on the time of thyroid disease manifestation." (PMID 24580798, 2014). "She had had type 2 diabetes, treated with insulin (basal-supported oral therapy) for three years before admission." (PMID 24524438, 2014). "Type 2 diabetes is characterized by increased fatty acid release from adipose tissue, impaired suppression of glucose output in the liver, and reduced insulin-stimulated glucose uptake in muscle." (PMID 25053966, 2014). "Indeed, several studies report reductions in visceral fat among healthy obese men and women, whereas others show increased levels of cardiorespiratory fitness, improved insulin sensitivity and improved fasting insulin, all of which may contribute to a lower risk of type 2 diabetes." (PMID 24661566, 2014). "a thiazolidinedione PPARγ agonist that modulates the transcription of insulin-sensitive genes and is used in the treatment of type 2 diabetes." (PMID 25481012, 2014). "In type-2 diabetes, β-cells secrete greater concentrations of insulin, the resulting hyperinsulinemia which stimulates IGF production; in mouse models of hypoinsulinemia had a significant prostate growth." (PMID 25332855, 2014). "IL-10 has a protective role in type 2 diabetes by increasing insulin sensitivity in skeletal muscle." (PMID 25302080, 2014). "According to the World Health Organization, type 2 diabetes comprises 90% of the total population with diabetes mellitus around the world, and is characterized by the body’s ineffective use of insulin." (PMID 25534067, 2014). "Our findings suggested that oral administration of CYSKT affected insulin signaling pathway, decreased HbA1c and blood glucose levels, and consequently reduced mortality rate in type 2 diabetic mice." (PMID 25133699, 2014). "Studies of visfatin, an adipokine highly expressed in visceral fat and up-regulated in obesity and type-2 diabetes, showed that it has insulin-mimetic effects in various cell lines." (PMID 24847313, 2014). "People with inadequately controlled type 2 diabetes (n = 99) were randomly assigned on a 1∶1∶1 basis to receive insulin glargin, with fixed doses of glimepiride, metformin, and glimepiride plus metformin." (PMID 24614911, 2014). "Significant independent determinants of weight reduction were baseline BMI and previous insulin therapy, suggesting that effect of liraglutide on weight reduction is further expected in obese type 2 diabetes patients with previous insulin therapy." (PMID 25237400, 2014). "Skeletal muscle is critical for people with type 2 diabetes, as it is the largest mass of insulin-sensitive tissue and the predominant reservoir for glucose disposal." (PMID 25376884, 2014). "Pioglitazone is an insulin sensitizer that acts through the nuclear receptor PPAR-γ, modulating the transcription of the insulin-sensitive genes and is highly effective oral medication for type 2 diabetes." (PMID 25210844, 2014). "Alloxan, as a cytotoxic agent to the insulin-secreting β cells of the pancreas, effectively induces insulin dependent phenotypes that resemble type 1 diabetes or post-beta cell “burnout” type 2 diabetes in a wide variety of animal models." (PMID 24891878, 2014).